TMPRSS2 (transmembrane serine protease 2)
Diseases named in the same sentence as TMPRSS2 in open-access papers (continued):
Sharing a sentence is not in itself a finding about the gene and the disease.
COVID-19 (continued). "In the present study, the inhibition mechanism of the Mpro of COVID-19 and the host receptor of TMPRSS2 with three ligands Dracocephin-A (L3), Phyllospadine (L6) and Prolin-A (L7) were studied step by step using molecular dynamics simulation in 100 ns." (PMID 38626042, 2024). "The study focused on the need for continued research to fully understand the role of TMPRSS2 in COVID-19 pathophysiology and its potential implications for disease management and treatment strategies." (PMID 39188881, 2024). "Higher levels of TMPRSS-2 have been postulated to be the etiology of increased disease severity in men with COVID-19 contributing to the observed sex differences in COVID-19." (PMID 39449074, 2024). "In the past pandemic years, several studies evaluated the possibility of using ACE2 and TMPRSS2 inhibitors as a treatment for COVID-19." (PMID 38606293, 2024). "Given that ACE2 and TMPRSS2 represent the major gateways for SARS-CoV-2 cell entry, their sex-dependent expression strongly advocates for COVID-19 studies which would take sex into account when investigating the role of ACE2 and TMPRSS2 polymorphism." (PMID 39744525, 2024). "Bromhexine is routinely used as a muco-active drug in upper respiratory tract infections; in this setting, given its activity on TMPRSS2, it was tested as an anti-COVID-19 drug." (PMID 38254788, 2024). "The role of TMPRSS2 in enhancing the infectivity of SARS-CoV-2 is of great significance in the pathogenesis of COVID-19." (PMID 38892254, 2024). "Considering the role of ACE2 and TMPRSS2 in COVID-19 pathogenesis and the variation in disease severity, rs2285666 and rs12329760 polymorphisms have attracted attention." (PMID 38263160, 2024). "The analysis of about 81,000 human genomes suggests a possible association between susceptibility, severity, and clinical outcomes of COVID-19 and ACE2 and TMPRSS2 DNA polymorphisms." (PMID 38263160, 2024). "In parallel, we examined the oral bioavailability of Paxlovid and camostat mesylate, which are clinically-approved Mpro and TMPRSS2 inhibitors for COVID-19 treatment." (PMID 39606435, 2024). "TMPRSS2 is a potential therapeutic target for COVID-19, and miR-98-5p is a regulatory factor of TMPRSS2 that originates from two types of endothelial cells in the lungs and umbilical vein." (PMID 38455049, 2024). "TMPRSS2 levels increased with disease severity in patients with COVID-19, consistent with prior reports." (PMID 39449074, 2024). "Studies have shown that alterations in polymorphisms within ACE2-spike protein interactions, the proteolytic cleavage site TMPRSS2, and ACE2 expression are correlated with the susceptibility and severity of COVID-19." (PMID 38638307, 2024). "The most well-studied TMPRSS2 inhibitor camostat mesylate were used to treat COVID-19 patients, yet has led to inconclusive outcomes." (PMID 39606435, 2024). "TMPRSS2 was previously suggested as a promising drug target for COVID-19 by using camostat mesylate, a drug approved for treating chronic pancreatitis and postoperative reflux esophagitis." (PMID 38855114, 2024). "This study showed a considerable rise in TNF-α and IL-1β serum levels exclusively in COVID-19 patients with TT rs2070788 TMPRSS2 SNP genotype compared to healthy controls." (PMID 39188881, 2024). "Since the thyroid gland, like the pancreas, contains receptors for SARS-CoV-2 (e.g., ACE2) and TMPRSS2 protein, it is likely that COVID-19 similarly disrupts its function at various molecular levels." (PMID 39767735, 2024). "Recent studies have shown that it can also inhibit the entry of COVID-19 into Caco-2 and Vero195 TMPRSS2 cells." (PMID 38892254, 2024). "Previous research suggested the potential of AZ on anti-COVID-19 activity through estrogen regulation and its effect on TMPRSS2 signaling." (PMID 38247540, 2024).
COVID-19 (continued). "Recently, it has been highlighted that GSH shows therapeutic potential against COVID-19 by interacting with human proteins such as TMPRSS2 (transmembrane serine protease 2) and ACE2 (angiotensin-converting enzyme 2)." (PMID 39334911, 2024). "We found that critically ill COVID-19 patients (the ones in ICU) had higher levels of TMPRSS-2 and aromatase, and lower testosterone levels." (PMID 39449074, 2024). "Several studies have highlighted the roles of the surface receptor for S1 of the ACE2 and the transmembrane protease serine-2 (TMPRSS2) receptor in subjects during the acute COVID-19 phase." (PMID 39200127, 2024). "To evaluate the potential of double-Tg mice to screen and develop therapeutic agents against COVID-19, we tested the TMPRSS2 inhibitor, nafamostat, whose inhibitory activity against SARS-CoV-2 infection is lost in the absence of TMPRSS217." (PMID 38816566, 2024). "Asymptomatic patients did not present significant differences in ACE2 levels, but there was a significant difference in TMPRSS2 levels before infection and during COVID-19 (p < 0.05)." (PMID 38606293, 2024). "This study evaluated possible associations between severity and outcome of COVID-19 and single nucleotide polymorphism (SNP) rs2285666 in the ACE2 gene and SNP rs2070788 in the TMPRSS2 gene." (PMID 39228902, 2024). "TMPRSS2 and aromatase were higher, while testosterone was lower in patients with increased COVID-19 severity." (PMID 39449074, 2024). "In conclusion, our study highlights association between the presence of TMPRSS2 rs2070788 and ACE2 rs2106809 polymorphisms, and the severity and outcome of COVID-19, respectively, among female patients." (PMID 39744525, 2024). "Associations between COVID-19 outcomes and single nucleotide polymorphisms of the ACE2 and TMPRSS2 genes, Faculty of Medicine, Zagazig University, Zagazig, Egypt, 01 July 2021 – 30 November 2021." (PMID 39228902, 2024). "During the COVID-19 period, special attention and medical care should be provided to patients with gastrointestinal malignancies, especially the elderly with elevated expression of ACE-2 and TMPRSS2, and severe forms of COVID-19 should be provided." (PMID 39050096, 2024). "In our study, a significant increase in IL-1β and TNF-α serum levels was exclusively observed in carriers of the TT genotype of the rs2070788 TMPRSS2 SNP in COVID-19 patients compared to healthy controls." (PMID 39188881, 2024). "This study shows that testosterone, aromatase, and TMPRSS2 are markers of COVID-19 severity in hospitalized patients." (PMID 39449074, 2024). "Next, it was critical to explore if there is any correlation between the prevalence of the identified SNVs of ACE2 and TMPRSS2 with the 24 investigated cytokines in COVID-19 patients and healthy controls." (PMID 38855114, 2024). "This is important and novel in the sense that post COVID-19 morbidities, and mortalities can be halted with a TMPRSS2 inhibitor." (PMID 38077924, 2023). "Proxalutamide as a novel potent AR antagonist has been shown to downregulate the expression of ACE2 and TMPRSS2 in lung cancer cells, and also accelerate viral clearance in mild to moderate patients with COVID-19." (PMID 37322522, 2023). "The expression of ACE-2 and TMPRSS2 on hepatocytes, cholangiocytes, and sinusoidal epithelial cells provides a potential for direct injury by COVID-19." (PMID 36979225, 2023). "Recently published systematic review and meta-analysis on the relation between ACE1, ACE2, TMPRSS2, IFITM3, and VDR genes polymorphisms and COVID-19 outcomes has elucidated the potential involvement of these SNPs in COVID-19 outcomes." (PMID 36743382, 2023). "The TMPRSS2 genotype of 251 COVID-19 patients (151 patients with asymptomatic to mild and 100 patients with severe to critical symptoms) was detected on genomic DNA extracted from patients’ peripheral blood via the ARMS-PCR method." (PMID 36795725, 2023).
COVID-19 (continued). "DHEA, as a type of androgen, has regulatory effects on the ACE-2 receptor and TMPRSS2, promoting the fusion of the SARS-CoV-2 virus into host cells, thereby increasing the susceptibility and severity of COVID-19." (PMID 36836216, 2023). "A previous study identified a proxy SNP (TMPRSS2 rs17854725 or c.879T > C) in a whole-exome scan of COVID-19 patients with familial multiple sclerosis, pointing to the possible involvement of the TMPRSS2 gene in cognitive-related phenotypes." (PMID 36675784, 2023). "Another key actor in this viral drama is transmembrane serine protease 2 (TMPRSS2), a membrane-bound serine protease that significantly influences COVID-19 pathogenesis." (PMID 37893162, 2023). "Here we characterize the role of ACE2, AR, MX1, ERG, ETV5 and TMPRSS2 for trying a better classification of COVID-19 through knowledge of the disease mechanisms." (PMID 37287057, 2023). "The TMPRSS2 gene, which is responsible for SARS-CoV-2 penetration into the cell, has been repeatedly implicated in COVID-19-related outcomes." (PMID 36675784, 2023). "Izmailova and colleagues aimed to investigate potential associations between the CD147 rs8259T>A, ACE2 rs4240157T>C, TMPRSS2 rs12329760C>T, and TMPRSS11A rs353163C/T variants and COVID-19 severity in the Ukrainian population." (PMID 37630479, 2023). "Summary of the antiviral agents targeting MPro and TMPRSS2 proteases as therapies for COVID-19 described in this review, and their approval state." (PMID 37375781, 2023). "Apart from IL-17, ACE2, and TMPRSS2, a complex interrelation also exists involving COVID-19, periodontitis, and melatonin." (PMID 37893162, 2023). "In a nutshell, the interaction between fibrin(ogen), D-dimer, P-selectin, VWF, and biomarkers like MMPs, ADAMTS-13, renal NGAL, PUMP, and TMPRSS2 intertwine within the context of acute COVID-19." (PMID 38077924, 2023). "Most drugs targeting TMPRSS2 as antiviral COVID-19 agents are repurposed TMPRSS2 inhibitors that have already shown activity in other types of diseases." (PMID 37375781, 2023). "By broadly capturing genetic variations related to COVID-19 outcomes, our PRS expands risk prediction capabilities beyond what is possible with analyses restricted to known loci like ACE2 and TMPRSS2." (PMID 38113267, 2023). "While some of the COVID-19 associated genes such as ACE2, TMPRSS2, and NRP1 were expressed in multiple organs, we did not detect significant viral mRNA load by RT-qPCR in the other organs processed." (PMID 37830426, 2023). "On the other hand, stabilization of a G4 within the mRNA of human TMPRSS2, which was elevated in the lungs of COVID-19 patients, inhibited TMPRSS2 translation leading to prevention of SARS-CoV-2 entry." (PMID 37006620, 2023). "SARS-CoV-2 employs the cellular serine protease TMPRSS2 for entry into lung cells, and TMPRSS2 inhibitors are being developed for COVID-19 therapy." (PMID 36851486, 2023). "Several studies explored the mechanism of TMPRSS2 regulation by AR and the possible applications for treating COVID-19." (PMID 36834705, 2023). "On the other hand, some studies on SNVs in COVID-19 have been focused on genes encoding SARS-CoV-2 receptors or on proteases that prime the S protein, such as ACE2 and TMPRSS2, respectively." (PMID 37630479, 2023). "Nevertheless, there is limited research available on the normal range of circulating TMPRSS2 levels in patients with COVID-19." (PMID 38444707, 2023). "The findings revealed a negative correlation between the levels of miR-200b-3p, miR-214-3p, ACE2, and TMPRSS2 in the peripheral blood of severe COVID-19 patients." (PMID 38444707, 2023). "As part of the research on COVID-19 treatments, several Casiopeina-analogs presented here were looked at as TMPRSS2 inhibitors." (PMID 36778030, 2023). "The significance of TMPRSS4 with similar function as TMPRSS2 in viral infection, has been suggested in smokers and its relation to COVID-19." (PMID 37041586, 2023).
COVID-19 (continued). "The expression of ACE-2 receptor and TMPRSS2 zona fasciculate and zona reticularis provides a target for COVID-19 invasion." (PMID 36979225, 2023). "Another TMPRSS2 inhibitor with broad distribution capability, bromhexine, has reduced the mortality of COVID-19 patients in clinical trials and is a potential therapeutic option as an inexpensive and safe over-the-counter drug." (PMID 37189326, 2023). "They noticed that ACE2 rs2285666 and TMPRSS2 rs12329760 SNPs can be predictors of COVID-19 severity." (PMID 36673116, 2023). "ACE-2 and TMPRSS2 are expressed in the pancreas, and its endocrine section can be a target for COVID-19." (PMID 36979225, 2023). "Another TMPRSS2 inhibitor, camostat, which is a serine protease inhibitor and used in the treatment of pancreatitis, has been repositioned as an anti-COVID-19 clinical candidate drug." (PMID 37126530, 2023). "Polymorphisms within ACE2 (rs2285666), TMPRSS2 (rs12329760), CD147 (rs8259) and NRP1 (rs10080) have been shown to associate with COVID-19 severity." (PMID 37761938, 2023). "Amid extensive efforts to design COVID-19 therapeutics, attempts have been made to disrupt TMPRSS2-related steps incumbent in SARS-CoV-2 infection." (PMID 37987478, 2023). "In that situation an inhibitor of proteinases, such as TMPRSS2 will be able to mitigate the COVID-19 induced CKD." (PMID 38077924, 2023). "STRING analysis corroborated these results, emphasizing the role of ACE2 and TMPRSS2 as interesting biomarkers of COVID-19." (PMID 37287057, 2023). "A significant association of exonic variants in the ACE2, TMPRSS2, and FURIN genes with COVID-19 incidence was detected by another research group using whole-exome sequencing." (PMID 36675784, 2023). "Much less is known about inhibitors of the other target of interest for COVID-19 therapies, the host protease TMPRSS2." (PMID 37375781, 2023). "Proteases such as furin, trypsin, TMPRSS2, and 3CLpro are potential targets for designing novel COVID-19 drugs." (PMID 36851526, 2023). "In comparison, results of a Google Scholar search for “TMPRSS2” (with results containing “COVID-19” and “SARS-CoV-2” filtered out) are dominated by studies on the protease’s role in various cancers rather than SARS-CoV." (PMID 36724184, 2023). "Regulation of the TMPRSS2 gene expression by androgen hormones has been suggested as one of the possible mechanisms explaining the difference in the severity of the COVID-19 between men and women." (PMID 36795725, 2023). "Several miRNAs, including miR-200b-3p, miR-214-3p, miR-200c-3p, miR-125b, miR-18, miR-98-5p, and miR-27b, have been identified as targeting ACE2, TMPRSS2, or other bioactive molecules involved in the pathological processes of COVID-19 and other viral diseases." (PMID 38444707, 2023). "In summary, the interaction between fibrin(ogen), D-dimer, P-selectin, VWF, and the mentioned biomarkers like MMPs, ADAMTS-13, renal NGAL, PUMP, and TMPRSS2 intertwines within the context of acute COVID-19." (PMID 38077924, 2023). "In COVID-19, TMPRSS2 plays a vital role in priming SARS-CoV-2 spike protein (S protein) binding to the ACE2 receptor for viral entry." (PMID 37529051, 2023). "Several studies have identified numerous genetic variants correlated with COVID-19 severity, including ACE2, ABO, CD26, IFITM3, HLA, TLR7, and TMPRSS2." (PMID 38138892, 2023). "Coincidentally, a recent study also reported a strategy for the broad-spectrum prevention and treatment of COVID-19 by targeting protease TMPRSS2, involved in viral entry." (PMID 37256962, 2023). "The severity of COVID-19 is, however, correlated with a number ofgenetic differences, such as TMPRSS2, interleukin 1B, TMPRSS2, and HLApolymorphisms." (PMID 38774857, 2023). "Our results are aligned with prior investigations demonstrating increased ACE2/TMPRSS2 expression in capillaries of COVID-19 patients, and therefore support capillaritis as a prominent mediator of viral-induced myocardial injury." (PMID 36968839, 2023).
COVID-19 (continued). "Intriguingly, the risk factors influencing SARS-CoV-2 infection and COVID-19 severity are complex and determined by target cell ACE2/TMPRSS2 expression and environmental exposure." (PMID 37243203, 2023). "The susceptibility to and progression of COVID-19 are thought to be correlated with genetic variations in angiotensin convertase enzyme (ACE) and transmembrane protease serine 2 (TMPRSS-2)." (PMID 36895544, 2023). "The soluble expression of TMPRSS2 in E. coli would facilitate downstream research on TMPRSS2–specific inhibitors discovery and ultimately promote COVID-19 therapy development." (PMID 37445653, 2023). "In preclinical research, the TMPRSS2 inhibitor nafamostat also reduced SARS-CoV-2 pulmonary infection in a mouse model of COVID-19." (PMID 37007494, 2023). "Our data presented in this and previous studies collectively demonstrated the existence of RG4 in at least four host factors (Ace2, Axl, Furin, and Tmprss2) that are considered as potential therapeutic targets for COVID-19." (PMID 36701392, 2023). "It has reappeared again as a drug of interest because of its ability as a TMPRSS2 inhibitor and hence a potential COVID-19 therapy." (PMID 37375781, 2023). "Two of the most studied genes are ACE2 and TMPRSS2, involved in SARS-CoV-2 entry, and some of their genetic variants have been associated with COVID-19 severity and infectivity." (PMID 37809329, 2023). "The comparison of a 6-gene signature (ACE2, TMPRSS2, AR, TLR7, IL6, and IRF5) was made to explore the sex-based differences associated with COVID-19." (PMID 36992366, 2023). "Camostat mesylate, an orally available and clinically used serine protease inhibitor, inhibits TMPRSS2, supporting clinical trials to investigate its use in COVID-19." (PMID 35412356, 2022). "Together, these findings are the first to demonstrate that small molecules, such as CD, AD, TQ, and TQFL12, inhibit TMPRSS2 expression, providing novel therapeutic strategies for preventing COVID-19 and cancers." (PMID 36364238, 2022). "Because SARS-CoV infection downregulates TMPRSS2 expression in cultured cells, we investigated the changes in TMPRSS2 expression in COVID-19-infected lungs." (PMID 36364238, 2022). "Several previous studies have established that the furin protease, alongside TMPRSS2, is a key human host protease essential for the viral spike protein maturation and entry into host cells, thus making furin an important anti-COVID-19 drug target." (PMID 36618412, 2022). "The serine protease inhibitor nafamostat is in clinical trials as a potential treatment for COVID-19, owing to its ability to inhibit TMPRSS2-mediated viral entry of SARS-CoV2 into lung epithelial cells." (PMID 34991643, 2022). "Why should COVID-19 reduce AR which is necessary for the production of the docking and internalization receptors (TMPRSS2 and ACE2)?" (PMID 35453608, 2022). "Receptors for SARS-CoV-2, ACE2 and TMPRSS2 are present in a wide variety of human cells, which is why COVID-19 targets on different systems from the human body." (PMID 36143878, 2022). "This process is supported by transmembrane protease serine 2 (TMPRSS2), which in COVID-19 leads to a robust immune response resulting in acute inflammation with increased levels of inflammatory mediators including cytokines and chemokines." (PMID 35401518, 2022). "TMPRSS2 was rare and limited to the bronchus and alveoli of healthy lung tissues, whereas it was increased in patients with COVID-19." (PMID 35301316, 2022). "At the moment, clinical studies are primarily investigating the anti-SARS-CoV-2 activity of TMPRSS2 inhibitors, with a focus on symptomatic and/or hospitalized COVID-19 patients." (PMID 35163273, 2022). "Bromhexine hydrochloride (BHH), which is used to reduce cough in children and adults, is another drug targeting TMPRSS2 activity, making it a potential therapeutic option in COVID-19." (PMID 35632833, 2022).